APOH (apolipoprotein H)
Diseases named in the same sentence as APOH in open-access papers (continued):
Sharing a sentence is not in itself a finding about the gene and the disease.
fatty liver (6 papers, 2022 to 2025). "Together, it is interesting to explore the potential regulatory mechanism of APOH in alcohol-associated fatty liver disease in this study." (PMID 36123743, 2022). "Apolipoprotein H (APOH) downregulation can cause hepatic steatosis and gut microbiota dysbiosis." (PMID 38101620, 2024). "In fatty liver mice model, downregulation of Apolipoprotein H gene was found to aggravate fatty liver and induce gut microbiota dysbiosis by dysregulating bile acids." (PMID 40435176, 2025). "In this study, we explored the potential mechanism by which ApoH deletion induced fatty liver disease." (PMID 38101620, 2024). "In our mouse model, we found that ApoH−/− mice clearly displayed fatty liver disease and increased serum TG levels than WT mice." (PMID 38101620, 2024). "In light of this, our findings suggest that APOH downregulation reduces HDCA production to promote hepatic steatosis by regulating the gut-liver axis." (PMID 38101620, 2024). "Other previously unreported variants associated with lipid traits and fatty liver disease, including rs2792735 in GPAM, rs2980888 in TRIB1, rs13389219 in COBLL1, rs8178824 in APOH and rs339969 in ICE2." (PMID 38632349, 2024). "In conclusion, in the present study, we aimed to elucidate the precise regulatory mechanism of APOH in hepatic steatosis." (PMID 38101620, 2024). "In the GSE162694 dataset, APOH expression gradually decreased in patients with hepatic steatosis during the progression of liver fibrosis (P < 0.05)." (PMID 38101620, 2024). "As cholesterol metabolism is a pivotal lipid metabolism regulatory pathway in the progression of hepatic steatosis, the profiles of sterol lipids in WT and ApoH−/− mice were further analyzed." (PMID 38101620, 2024). "Overall, this study provides a valuable framework for deciphering the role of APOH in the pathogenesis of fatty liver disease and enabling newer therapeutic explorations." (PMID 38101620, 2024). "Through these alterations, APOH downregulation aggravates fatty liver and is involved in MASLD pathogenesis." (PMID 38101620, 2024). "Severe hepatic steatosis was observed in alcohol-fed WT and ApoH−/− mice, in which ApoH expression was reduced post alcohol consumption." (PMID 36123743, 2022). "Alcohol-downregulated ApoH expression, leading to the progress of fatty liver disease and gut microbiota dysbiosis." (PMID 36123743, 2022). "Downregulation of ApoH has been implicated in non-thrombotic conditions, such as exacerbating fatty liver disease and disrupting gut microbiota homeostasis, pointing to its involvement in metabolic and inflammatory pathways." (PMID 40137160, 2025). "Second, the study findings may not adequately reflect the findings observed in clinical settings; therefore, additional in-depth studies investigating the role of APOH using animal models of fatty liver disease are needed." (PMID 38101620, 2024). "At first, considering the spectrum of MASLD, including fatty liver, steatohepatitis, fibrosis, cirrhosis, or liver cancer, we speculate that APOH downregulation-induced fatty liver might be an early pathologic change and could evolve into hepatitis or fibrosis during disease progression." (PMID 38101620, 2024). "Considering the downregulation of APOH might be an initial factor to break the balance of enterohepatic circulation, it is valuable to exploit a favorable treatment target for maintaining the metabolic balance of the body and bring a new therapeutic strategy for fatty liver disease." (PMID 36123743, 2022).
hyperlipidemia (6 papers, 2017 to 2025). "The result significantly showed that DEFAs were closely related to Apolipoprotein (APOH), which was related to hyperlipidemia and closely related to the incidence of CRC." (PMID 36703795, 2022). "A clinical research has found that the concentration of ApoH increases in patients with hyperlipidemia, and this observation suggests a close link between plasma lipoprotein and ApoH." (PMID 28883884, 2017).
Obesity (6 papers, 2010 to 2022). Accumulation of substantial excess body fat. "ApoH accumulation was significantly increased in relation to BMI, showing statistical differences in OW and obesity groups." (PMID 28425473, 2017). "IL-6, IL-1β and APOH were identified as regulatory factors involved in blood coagulation and platelet activation in zebrafish and mammalian obesity." (PMID 20961460, 2010). "However, the effect of APOH binding to APC is inconclusive and the functional role of APOH in obesity remains to be elucidated." (PMID 20961460, 2010). "Additionally, we also observed that overweight and obesity among ALL survivors were positively correlated with the levels of Apo-C3, apolipoprotein H (Apo-H), Apo-J, and CRP (Apo-C3: r = 0.60; Apo-H: r = 0.49; Apo-J: r = 0.41; CRP: r = 0.47; p < 0.05; )." (PMID 36142534, 2022).
viral infection (6 papers, 2020 to 2023). "Taken together, we propose that APOH might play different roles in acute versus chronic HBV infection, and the potential sex-synergistic effect might be another hinge point between APOH and viral infection." (PMID 36852272, 2023). "It has been known that APOH is an acute-phase protein in viral infection." (PMID 36852272, 2023). "We considered that APOH performs additional functions during chronic HBV infection, besides acting as an acute-phase protein in viral infection." (PMID 36852272, 2023).
colorectal cancer (5 papers, 2021 to 2025). A primary or metastatic malignant neoplasm that affects the colon or rectum. "β-2-glycoprotein 1 (APOH) has been shown to be associated with liver metastasis from colorectal cancer." (PMID 35449866, 2022). "Recently, several studies found that APOH is a key hub gene in colorectal cancer liver metastasis, and colorectal cancer patients with metastasis with higher levels of APOH expression also had worse prognoses and survival." (PMID 37770976, 2023).
dementia (4 papers, 2011 to 2021). Loss of intellectual abilities interfering with an individual's social and occupational functions. "Only a single study is available, showing elevated ApoH in the CSF of several dementia subtypes." (PMID 22701550, 2012). "ApoH is involved in diverse physiological processes, including lipid metabolism, however, little is known about the role if any that this protein may play in MCI or dementia." (PMID 22701550, 2012).
hepatitis B (4 papers, 2018 to 2025). "Similarly, APOH has been found to induce ER stress during hepatitis B infection, APOB100 is associated with lipid-induced ER stress and hepatic insulin resistance, and APOCIII has been shown to cause ER stress and inflammation, while also impairing insulin signaling in mouse skeletal muscle cells." (PMID 41366770, 2025). "The previous study was focused on the function of apolipoprotein H (APOH) during hepatitis B infection." (PMID 36123743, 2022).
liver cancer (4 papers, 2022 to 2024). An epithelial or non-epithelial malignant neoplasm that arises from the liver.
melanoma (4 papers, 2021 to 2025). A malignant, usually aggressive tumor composed of atypical, neoplastic melanocytes. "Eleven genes were significantly differentially expressed between metastases and primary tumors, and ALB, ORM2, CRABP1, and APOH may be associated with the metastasis of melanoma." (PMID 34154655, 2021). "APOH was negatively correlated with regulatory T cells in primary melanomas, whereas VAV2 was positively correlated with CD8 T cells, but negatively with dendritic cells." (PMID 40943183, 2025). "There is no relevant functional study on the relationship between ALB, ORM2, CRABP1, and APOH and melanoma metastasis, which may represent future candidates." (PMID 34154655, 2021). "As a methodology, SFD is able to reveal well-known proteins in melanoma exosomes that are immune-related and are also surface-expressed proteins, such as CD26 (DPP4), CD44, CALR, B7-H3 (CD276), CSF1, ICAM1, L1CAM, MICB, APOH, TIMP1, and CD39." (PMID 40805206, 2025).
steatosis (4 papers, 2022 to 2024). Increased lipid within the cytoplasm of cells. "In our previous studies, we found that APOH downregulation causes hepatocyte steatosis and that alcohol-dependent APOH downregulation exacerbates fatty liver and gut microbiota dysbiosis in mice." (PMID 38101620, 2024). "In this study, we aimed to elucidate the potential regulatory role of APOH in MASLD development and investigate the association between APOH levels, hepatocyte steatosis, and gut microbiota dysbiosis." (PMID 38101620, 2024). "Additionally, we observed apparent steatosis in the hematoxylin and eosin–stained liver sections of ApoH−/− mice." (PMID 38101620, 2024). "Furthermore, significant levels of hepatocyte steatosis were observed in ApoH−/− mice with a persistent HBV infection." (PMID 36852272, 2023). "In the present study, we analyzed the serum APOH levels in patients with HBV-related chronic liver diseases and utilized the HepG2.2.15 cell line and an ApoH−/−plus HBV replication mouse model to further investigate the effect of APOH on hepatocyte steatosis and gut microbiota dysbiosis." (PMID 36852272, 2023). "Furthermore, ApoH reduces the intracellular accumulation of cholesterol and blocks the oxidation of LDL31, which in turn inhibits steatosis development." (PMID 35383209, 2022).
Cognitive impairment (3 papers, 2012 to 2024). Abnormal cognition is characterized by deficits in thinking, reasoning, or remembering. "ApoA1, ApoH and ApoJ may be potential clinical biomarkers for cognitive impairment." (PMID 22701550, 2012). "Furthermore, including lipid profile as covariates did not affect the ability of ApoA1, ApoA2 and ApoH levels and ApoB/ApoA1 ratio to predict cognitive impairment." (PMID 22701550, 2012).
Influenza infection (3 papers, 2019 to 2024). "The analysis of blood levels of ApoH in influenza patients showed that low levels were associated with severe forms, indicating that this molecule behaves as a protective factor for the development of severe forms of the disease, especially those related to RF and hospitalization to ICU." (PMID 39176097, 2024). "Adequate plasma levels of ApoH are protective against severe influenza and RF and High levels of IL15 protect against RF." (PMID 39176097, 2024). "ApoH replacement therapy in patients with severe influenza and very low levels of the protein may be a suitable alternative." (PMID 39176097, 2024). "Furthermore, ApoH levels in the entire cohort of influenza patients were significantly lower than those observed in healthy controls." (PMID 39176097, 2024).
alcoholic fatty liver disease (2 papers, 2022 to 2024). Lipid infiltration of the hepatic parenchymal cells that is due to alcohol abuse. "For example, alcohol downregulates ApoH expression, exacerbates fatty liver, and induces dysbiosis of lipid metabolism in a mouse model of alcoholic fatty liver disease (AFLD)." (PMID 39353906, 2024). "Further studies should examine the accurate regulatory mechanism of ApoH-related lipid metabolism and concomitant gut microbiota metabolism in alcoholic and non-alcoholic fatty liver diseases." (PMID 36123743, 2022). "ApoH−/− mice were generated and the synergic alcoholic steatohepatitis mouse model was constructed, which were used to assess liver function and pathological changes." (PMID 36123743, 2022).
cognitive decline (2 papers, 2012 to 2024). "Lower ApoA1, ApoA2 and ApoH levels, and higher ApoB/ApoA1 ratio, increased the risk of cognitive decline over two years in cognitively normal individuals." (PMID 22701550, 2012). "In summary, participants with lower ApoA1, ApoA2, ApoH levels or higher ApoB/ApoA1, at Wave 1 had a higher risk of future cognitive decline." (PMID 22701550, 2012). "Our results showed that MCI subjects had a lower level of ApoH in the cross-sectional comparison, and low levels of ApoH also increased the risk of cognitive decline during follow-up." (PMID 22701550, 2012). "ApoA1, ApoH and ApoJ are potential plasma biomarkers of cognitive decline in non-demented elderly individuals." (PMID 22701550, 2012).
depression (2 papers, 2015 to 2023). "Out of our 26-analyte panel, only three proteins (ApoH, ApoA1 and B2M) were altered in bipolar disorder patients and four (MIF, ACE, TNC and ILra) were changed in patients with depression." (PMID 26171982, 2015).
Hypercholesterolemia (2 papers, 2014 to 2019). An increased concentration of cholesterol in the blood. "Polymorphism in apolipoprotein H (APOH) was linked with progression of hypercholesterolemia, but this polymorphic gene may be liable for development of CAD." (PMID 31881747, 2019).
iron deficiency (2 papers, 2019 to 2020). "It has been shown that iron deficiency upregulates lipogenic genes but downregulates apolipoprotein H and genes involved in the mitochondrial beta-oxidation, resulting in increased circulating lipids." (PMID 33080795, 2020). "Moreover, a study conducted with iron-deficient rats reported that iron deficiency also affected lipid metabolism by down-regulating Apolipoprotein H expression, which although not thoroughly studied, has been related to increased cholesterol, TG and LDL in plasma." (PMID 30755213, 2019).
lymphoma (2 papers, 2022 to 2025). A malignant (clonal) proliferation of B- lymphocytes or T- lymphocytes which involves the lymph nodes, bone marrow and/or extranodal sites. "No study has previously reported the increased expression of Ig heavy chain V region GOM associated with canine lymphoma in the same way as with TIMP-1, APOH, and CD44." (PMID 35765478, 2022). "The first reported serum proteins in canine lymphoma were ACTB, Ig heavy chain V region GOM, TIMP-1, APOH, CD44, APOC1, and β2M." (PMID 35765478, 2022). "Potential novel candidate biomarkers in canine lymphoma were ACTB, β2M, TIMP-1, CD44 antigen, Ig heavy chain V region GOM, APOC1, and APOH." (PMID 35765478, 2022). "Six candidate increased proteins in canine lymphomas were beta-actin cytoplasmic 1 (ACTB, p=0.04), haptoglobin (p=0.002), beta-2 microglobulin (aaaaaaaa2M, p=0.007), beta-2 glycoprotein 1 (APOH, p=0.03), metalloproteinase inhibitor 1 (TIMP-1, p=0.03), and CD44 antigen (p=0.02)." (PMID 35765478, 2022). "Differently higher serum proteins in canine lymphoma were observed in beta-actin cytoplasmic 1 (ACTB, p=0.04), Hp (p=0.002), beta-2 microglobulin (β2M, p=0.007), beta-2 glycoprotein 1 (APOH, p=0.03), metalloproteinase inhibitor 1 (TIMP-1, p=0.03), and CD44 antigen (p=0.02)." (PMID 35765478, 2022). "ACTB, aaaaaaaa2M, APOH, TIMP-1, CD44 antigen, Ig heavy chain V region GOM, and APOC1 are novel candidate proteins and might serve as a lymphoma biomarker in dogs." (PMID 35765478, 2022).
alcoholic hepatitis (1 paper, 2022). Acute hepatitis resulting from ingestion of alcohol. "Our mouse model of alcoholic hepatitis in an ApoH−/− background highlighted the impact of alcohol on liver dysfunction." (PMID 36123743, 2022).
allergic rhinitis (1 paper, 2025). Inflammation of the nasal mucous membranes caused by an IgE-mediated response to external allergens. "The proteins ORM, APOH, FGA, CTSD, and SERPINB3, which showed promise in preclinical studies for predicting response to glucocorticoids, have also been evaluated in clinical trials involving patients with seasonal allergic rhinitis (SAR)." (PMID 40551926, 2025).
anaphylaxis (1 paper, 2021). An acute hypersensitivity reaction that occurs from exposure to an allergen. "Other protein related with coagulation processes have been found increased in EC-anaphylaxis: PROC, PROS, APOH, Galectin-3 and TSP1." (PMID 34248989, 2021).
atrial fibrillation (1 paper, 2022). A disorder characterized by an electrocardiographic finding of a supraventricular arrhythmia characterized by the replacement of consistent P waves by rapid oscillations or fibrillatory waves that vary in size, shape and timing and are accompanied by an irregular ventricular response. "The missense variant p.Cys325Gly in APOH was also associated with increased risk of atrial fibrillation (P = 3.5 × 10−9, OR = 1.12, ncases = 96,018), heart failure (P = 2.4 × 10−9, OR = 1.12, ncases = 99,214) and higher levels of lipoprotein (a) (Lp(a); P = 2.2 × 10−56, effect = 0.10 s.d)." (PMID 36280732, 2022).
cholelithiasis (1 paper, 2025). The presence of crystallized deposits forming in the gallbladder or biliary tree, primarily composed of cholesterol, bilirubin, and bile. "Seven genes, including GCKR, SNX17, ABCG8, MARCH8, FUT2, APOH, and HNF1A, were revealed to be colocalized with the causal signal between sphingomyelin and cholelithiasis." (PMID 40428345, 2025).
graft versus host disease (1 paper, 2022). An immune system disorder that occurs after allogeneic hematopoietic stem cell transplant and is a reaction of donor immune cells against host tissues. "Our result presented the same trend as ANGPTL3 and ApoH genes were both reduced in IF/TA group, and we observed that those genes were both related to allograft rejection and graft-versus-host disease." (PMID 35755170, 2022).
hemophilia B (1 paper, 2020). Hemophilia B is a form of hemophilia characterized by spontaneous or prolonged hemorrhages due to factor IX deficiency. "INS regulates vascularization; APOH, F2, and ICAM regulate platelet activation and adhesion; AGT regulates blood vessel contraction; TNF and CCL2 regulate blood chemokine in circulation; F9 regulates onset Hemophilia B, and PON1 inhibits onset cardiovascular disease." (PMID 32753925, 2020).
hyperferritinemia (1 paper, 2024). "In multivariate analysis, low plasma levels of ApoH (OR:5.43; 2.21-13.4), high levels of C- reactive protein (OR:2.73: 1.28-5.4), hyperferritinemia (OR:2.83; 1.28-5.4) and smoking (OR:3.41; 1.04-11.16), were significantly associated with a worse prognosis." (PMID 39176097, 2024).
injury (1 paper, 2024). Damage inflicted on the body as the direct or indirect result of an external force, with or without disruption of structural continuity. "In parallel, we did not identify a direct biologicalconnectionbetween Ncan–APOH and TYR or Ncan–TMEM 212 and FSIP2in the context of brain injury." (PMID 38870483, 2024).
liver cirrhosis (1 paper, 2025). "Additionally, another six genes (ALB, APOH, FABP1, FGB, FGG, and TF) were identified from our previous HCC EV-specific gene panel given their performance in distinguishing early-stage HCC from liver cirrhosis." (PMID 40307890, 2025).
lung carcinoma (1 paper, 2023). "For instance, based on the soft clustering method and nested comparisons, we found that MUC5B and SELL have potential diagnostic values for lung cancer cases of BM, and the best accuracy was achieved when separating cases of BM and LA from LM using the combination of APOH, CD81, and CCT5." (PMID 37770976, 2023).
papillary lung adenocarcinoma (1 paper, 2023). A morphologic variant of lung adenocarcinoma characterized by the presence of papillary structures. "Likewise, APOH was upregulated in papillary lung adenocarcinomas in mice; however, in mice with atypical adenomatous hyperplasia (AAH) of the lung, their APOH was downregulated by twofold." (PMID 38067270, 2023).
periodontal diseases (1 paper, 2018). "Four proteins (Beta-2-glycoprotein I (APOH); α-fibrinogen (FIBA); Hemopexin (HEMO); Plasminogen (PLMN)) were found to be present at statistically different levels between groups, and are promising candidates to facilitate screening and diagnosis of periodontal diseases." (PMID 29900194, 2018).